HBE1 (hemoglobin subunit epsilon 1)
Description:
The epsilon chain is a beta-type chain of early mammalian embryonic hemoglobin.
Synonyms: HBE
Tractability: Small molecule: a structure with a bound ligand is known. PROTAC: ubiquitination databases record sites on it.
Gene: Protein-coding gene on chromosome 11 (5,268,345 to 5,505,652, reverse strand). Ensembl gene ENSG00000213931.
Pathways (Reactome):
Hemostasis: Factors involved in megakaryocyte development and platelet production
Gene Ontology:
Molecular function: protein binding; heme binding; hemoglobin alpha binding; oxygen carrier activity; oxygen binding
Biological process: oxygen transport; carbon dioxide transport; erythrocyte development
Cellular component: blood microparticle; hemoglobin complex; cytosol; haptoglobin-hemoglobin complex
Genetic constraint (gnomAD): Loss-of-function variants: 9 observed, 9.68 expected, observed/expected ratio (o/e) 0.93, 90% interval 0.56 to 1.6. That is too few expected variants to judge how well the gene tolerates losing a copy. Missense variants: 162 observed, 176.98 expected, observed/expected ratio (o/e) 0.92, 90% interval 0.81 to 1.04. Synonymous variants: 75 observed, 72.32 expected, observed/expected ratio (o/e) 1.04, 90% interval 0.86 to 1.26.
Homologues: Orthologues: chimpanzee HBE1 (100% identical), rat Hbe1 (82% identical), mouse Hbb-y (81% identical), zebrafish hbba2 (54% identical), zebrafish hbbe2 (54% identical), zebrafish ba1l (53% identical), zebrafish hbba1 (53% identical), zebrafish hbbe3 (52% identical), zebrafish hbbe1.2 (52% identical), zebrafish hbbe1.3 (52% identical), tropical clawed frog hbg1 (48% identical), zebrafish hbbe1.1 (31% identical), and 3 more. Paralogues in human: HBG1 (80% identical), HBG2 (80% identical), HBB (76% identical), HBD (73% identical), HBA1 (38% identical), HBA2 (38% identical), HBZ (38% identical), HBQ1 (36% identical), HBM (35% identical), CYGB (29% identical), MB (23% identical).
Diseases named in the same sentence as HBE1 in open-access papers:
HBE1 is named in the same sentence as 63 diseases in open-access papers, as found by Europe PMC text mining. Sharing a sentence is not in itself a finding about the gene and the disease. The quoted sentences say what the papers report.
thalassemia (33 papers, 2008 to 2025). An inherited blood disorder characterized by a decreased synthesis of one of the polypeptide chains that form hemoglobin. "Genes encoding embryonic hemoglobin and HbF, including HBE1 and HGB1, have been targeted as part of possible therapies in thalassemias, where reactivating these alternative forms of hemoglobin expression may help to supplement low HbA production." (PMID 40306283, 2025). "Above defined variants of HBA2, HBE1 and HBG1 might confer the thalassemia phenotype in the Pakistani population." (PMID 37580329, 2023).
anemia (13 papers, 2013 to 2025). A reduction in the number of red blood cells, the amount of hemoglobin, and/or the volume of packed red blood cells. "In addition, the potentially related diseases to specific patients’ proteins were anemias or hematopoietic system diseases (proteins HBZ, EPB41, HP, PGK1, HBE1, BPGM, and ALDOA)." (PMID 36519745, 2022).
hemoglobinopathies (11 papers, 2010 to 2026). "Numerous other hemoglobinopathy-associated loci have emerged, such as rs2213169, rs2213170, and rs7130110 markers, which are neighbors to HBE1 and HBG2 genes." (PMID 40141459, 2025).
malaria (9 papers, 2011 to 2025). Malaria is a serious and sometimes fatal disease caused by a parasite that commonly infects a certain type of mosquito which feeds on humans. "Similarly, CSMD1 and the HBE1, HBG2 and HPSE2 genes were identified as candidates for positive selection in both NA and WEA populations, probably because of the historical presence of malaria in both Sub-Saharan Africa and the Mediterranean region as a common selective pressure." (PMID 37210386, 2023).
beta thalassemia (8 papers, 2017 to 2025). Beta-thalassemia (BT) is characterized by deficiency (Beta+) or absence (Beta0) of synthesis of the beta globin chains of hemoglobin (Hb). "In addition to the sickle trait gene (HBB), our mapping strategies identified other members of beta globin gene cluster that cause various forms of beta-thalassemia (HBE1, HBD, HBG, and HBG2)." (PMID 34868193, 2021). "Five genes mapped to hemoglobin subunits (HBG1, HBG2, HBE1, HBB and HBD) involved in beta thalassemia and fetal hemoglobin quantitative trait locus 1 diseases." (PMID 38627641, 2024).
colorectal cancer (2 papers, 2019 to 2022). A primary or metastatic malignant neoplasm that affects the colon or rectum. "Different types of Hbs (including HBE1 and HBZ) have been detected in glioblastoma cell lines, while HBE1 has been associated with radio-resistance in colorectal cancer cells." (PMID 36519745, 2022). "By comparing RNA-seq data from several colorectal cancer (CRC) cell lines with differing radiation sensitivities, we identified a candidate radiation resistance-associated gene, namely, epsilon-globin (HBE1)." (PMID 30965648, 2019). "Collectively, these observations indicate that the expression of HBE1 during radiotherapy might potentiate the survival of radiation-exposed colorectal cancer cells." (PMID 30965648, 2019).
follicular adenoma (1 paper, 2016). "In differentiating between follicular adenoma, follicular carcinoma, and the follicular variant of PTC, several biomarkers have proved to be applicable, including LGALS, hemoglobin, epsilon 1 (HBE1), cytokeratin-19 (CK-19), and thyroid peroxidase (TPO)." (PMID 27213120, 2016).
gallbladder cancer (1 paper, 2024). "A comparative analysis of differential proteomic data revealed 7 hypermethylated or down-regulated genes (e.g., FBN1, LPP, SOD3) and 61 hypomethylated or up-regulated genes (e.g., HBE1, SNRPF, TPD52), which contributed to the early diagnosis of gallbladder cancer." (PMID 38427106, 2024).
metastatic tumor (1 paper, 2019). "The expression of HBE1 might lead to the attenuation of radiation-induced cell death, based on its effects on radiation resistance and ROS generation, which might not be evident by analyzing established primary or metastatic tumor specimens." (PMID 30965648, 2019). "It is noteworthy that the marked overexpression of HBE1, evident in radiation-resistant CRC cells, does not occur in either primary tumors or in metastatic tumors, but rather reflects the transient state of cancer cells in the vasculature." (PMID 30965648, 2019).
cancer (5 papers, 2004 to 2020). A tumor composed of atypical neoplastic, often pleomorphic cells that invade other tissues. "In the present study, radiation-resistant (RR) cancer cells were established by sequential radiation exposure, and hemoglobin subunit epsilon 1 (HBE1) was identified as a candidate radiation resistance-associated protein based on RNA-sequencing analysis." (PMID 30965648, 2019). "There is no previous report of HBE1’s expression in cancer cells." (PMID 24934327, 2015).
blood disorders (3 papers, 2008 to 2025). "Hemoglobin subunit epsilon 1 (HBE1) plays a crucial role in treating different hematologic disorders and blood cancer, but extensive CO negatively affects the functions of HBE1." (PMID 40238577, 2025).
HBE1 also shares sentences with these, for which no sentence is quoted: infection (45 papers); hepatitis B (18); chronic hepatitis B (15); Hepatitis (14); hepatocellular carcinoma (12); liver disease (11); chronic hepatitis (10); Cirrhosis (10); tumor (9); co-infection (8); liver cirrhosis (5); liver fibrosis (5); sickle cell anaemia (5); Acute hepatitis (3); Alpha-thalassemia (3); Iron deficiency anemia (3); endothelial dysfunction (2); G6PD deficiency (2); hemochromatosis (2); leukocytosis (2); syphilis (2); viral hepatitis (2); AIDS (1); Arthritis (1); blood cancer (1); brain tumors (1); central obesity (1); cerebral malaria (1); chronic hepatitis C (1); colon cancer (1).
A further 22 diseases each share a sentence with HBE1 in 1 paper.